PTH (parathyroid hormone)
Diseases named in the same sentence as PTH in open-access papers (continued):
Sharing a sentence is not in itself a finding about the gene and the disease.
Hypocalcemia (continued). "Pseudohypoparathyroidism (PHP) indicates a rare heterogeneous group of disorders characterized by hypocalcemia, hyperphosphatemia, increased serum concentration of parathyroid hormone (PTH), and insensitivity to the biologic activity of PTH." (PMID 35600030, 2022). "After thyroidectomy, monitoring of PTH and serum calcium levels is mandatory for identifying the hypoparathyroidism before the development of severe and symptomatic hypocalcemia." (PMID 34575224, 2021). "Postoperative PTH levels are significantly related to postoperative hypocalcemia, and a recent systematic review showed that patients with a decrease in post-operative PTH had a 69–100% chance of developing temporary hypocalcemia." (PMID 34575224, 2021). "The assessment of early post-operative serum PTH helps predict the subsequent development of hypocalcemia." (PMID 34574074, 2021). "There was a significant correlation between the 3-h postoperative PTH level and the development of hypocalcemia within 48 h after surgery (p < 0.001)." (PMID 34574074, 2021). "Recombinant human parathyroid hormone (rhPTH 1-84, Natpara) is approved in the US for the management of hypocalcemia in hypoparathyroidism in addition to Ca+2 and vitamin D." (PMID 33542868, 2021). "The accuracy of a single PTH concentration at 48 h was useful for predicting hypocalcemia [Area under receiver–operator characteristic curve (AUC) 1; confidence interval (CI), 95%, 0.85–0.94]." (PMID 34429957, 2021). "Dysfunction of PTH is highly prevalent in the critical illnesses, and hypocalcemia is common in critically ill patients." (PMID 33936225, 2021). "Patients with elevated PTH and creatinine due to CKD can have hypocalcemia associated with secondary hyperparathyroidism." (PMID 33542868, 2021). "The ROC curve analysis indicated that the best cutoff for PTH was 9.4 pg/ml with a sensitivity of 84.9% and a specificity of 71.4% to predict hypocalcemia." (PMID 34956363, 2021). "A decrease of extracellular ionized calcium concentration (hypocalcemia) induces a marked increase in PTH synthesis and secretion from the parathyroid glands." (PMID 34746197, 2021). "In our previous preliminary study, we found that relative 70% decline of PTH was a reasonable indicator of clinical hypocalcemia at 4.67% vs. 27.0% in patients with relative decline of ≤70% and >70%, respectively." (PMID 33762946, 2021). "This study aims to evaluate the capacity of early serum PTH to predict the development of post-surgical hypocalcemia after thyroidectomy." (PMID 34574074, 2021). "Postsurgical HypoPT is suspected in patients with symptomatic or asymptomatic hypocalcemia and low or inappropriately ‘normal’ PTH concentrations." (PMID 34863037, 2021). "In both cases, the elevation in PTH (488 pg/mL and 287 pg/mL) was likely multifactorial; initially as a feedback to hypocalcemia in the setting of denosumab." (PMID 33191899, 2021). "In particular, these disorders are mainly characterized by the resistance to biological actions of the parathyroid hormone, resulting in hypocalcaemia and hyperphosphataemia, in the presence of high PTH levels." (PMID 33663571, 2021). "Univariate analysis showed that age (p = 0.03), postoperative PTH concentration (p = 0.02), and anatomopathological diagnosis of malignancy (p = 0.002) were predictors of postoperative hypocalcemia." (PMID 31492617, 2021). "The evaluation of serum parathyroid hormone (PTH) levels after thyroidectomy represents a reliable method to predict post-thyroidectomy hypocalcemia, but it remains infrequently used." (PMID 34574074, 2021). "Autosomal dominant hypocalcaemia type 1 (ADH1) is a genetic disease characterized by benign hypocalcemia, inappropriately low parathyroid hormone levels and mostly hypercalciuria." (PMID 34160437, 2021). "It is well established that the postoperative calcium level predicts symptomatic hypocalcemia after surgery, and the calcium level is regulated by vitamin D and parathyroid hormone." (PMID 33762946, 2021).
Hypocalcemia (continued). "In critically ill patients, hypocalcemia and increased levels of intact serum PTH are common early findings." (PMID 34895160, 2021). "Calcitriol synthesis, and consequently Ca/Pi serum levels, are increased by hypocalcemia, hypophosphatemia, and PTH while are decreased by calcitriol and FGF23." (PMID 34199067, 2021). "Preoperative PTH was scarcely discussed in previous studies about its effect on postoperative hypoparathyroidism or hypocalcemia." (PMID 34956363, 2021). "PTH acts on bone, kidney and intestine, and is produced in response to hypocalcemia and hyperphosphatemia, as well as low 1,25(OH)2D3 and FGF23." (PMID 34360805, 2021). "Secondary outcome is the assessment of postoperative biochemical (calcium and PTH levels) and clinical hypocalcemia (symptoms as reported by the patient)." (PMID 35071309, 2021). "Pseudohypoparathyroidism is a rare disorder that is characterized by hypocalcemia and hyperphosphatemia that are unresponsive to the parathyroid hormone." (PMID 34373806, 2021). "Hypoparathyroidism is characterized by inadequate production of PTH, leading to hypocalcemia and hyperphosphatemia." (PMID 33925967, 2021). "Receiver operating characteristics (ROC) curve was used to define the best cut off value of Total Calcium, and PTH, The accuracy of a single PTH concentration at 48 h was good for predicting hypocalcemia [AUC 1; CI, 95%, 0.85–0.94]." (PMID 34429957, 2021). "The biochemical findings are hypocalcaemia, hypophosphatemia, elevated PTH levels due to secondary hyperparathyroidism, increased ALP activity and low urinary Ca2+ excretion." (PMID 34068220, 2021). "Serum investigations revealed hypocalcemia and low levels of parathyroid hormone and thyroid-stimulating hormone." (PMID 34345548, 2021). "Postoperative hypocalcemia can be related to hypoparathyroidism (inappropriate low PTH in relation to calcium concentration), accompanied by a high phosphate concentration." (PMID 34863037, 2021). "Relative absolute fluorescence intensity was predictive of both postoperative hypocalcemia (p = 0.027) and a postoperative drop in parathyroid hormone (p < 0.001)." (PMID 34064948, 2021). "sHPT was triggered by hypocalcemia, hyperphosphatemia, and bone resistance to PTH in patients with CRF failure." (PMID 33991027, 2021). "With regard to our study, cutoff point of PTH 10 min after TT of 23 pg/mL as has been the best compromise between sensitivity and specificity for predicting hypocalcemia." (PMID 34429957, 2021). "Mg deficit-related hypocalcemia secondary to peripheral PTH resistance or decreased PTH secretion is further complicated by the loss of PTH stimulation of renal 1-alpha-hydroxylation with worsening vitamin D deficit." (PMID 33435521, 2021). "In patients with CKD stages 4-5D with severe SHPT, denosumab promoted marked hypocalcemia and increased PTH level within the first 15 days of its administration, which often required calcium supplementation." (PMID 33219822, 2021). "When there is surgical injury to the parathyroid glands, insufficient PTH secretion occurs and, consequently, hypocalcemia develops." (PMID 34082812, 2021). "Patients with PHP present with hypocalcaemia, hyperphosphatemia, diminished serum concentration of 1,25(OH)2D3, and increased serum PTH concentration." (PMID 34068220, 2021). "Etiology for hypophosphatemia was initially thought to be secondary hyperparathyroidism given elevated parathyroid hormone (PTH) of 488 pg/mL (12 – 88 pg/mL) due to hypocalcemia in the setting of recent denosumab administration." (PMID 33191899, 2021). "Where preoperative PTH and calcium are high, monitoring of calcium level in the early post-operative period is imperative to avoid hypocalcemia and its deleterious complications." (PMID 34450530, 2021). "This retrospective study investigates serum PTH values 3 h after thyroidectomy as a predictor of hypocalcemia." (PMID 34574074, 2021).
Hypocalcemia (continued). "In our previous research, 70% relative decline of PTH (RDP) was selected as a cutoff to predict clinical hypocalcemia." (PMID 33762946, 2021). "On the one hand, low preoperative vitamin D and low postoperative parathyroid hormone levels were seen as predictors for the development of hypocalcemia." (PMID 35071309, 2021). "PTH release is triggered by hypocalcemia and modulated by prostaglandin E2, dopamine, and adrenergic agonists." (PMID 35299844, 2021). "The researchers are trying to evaluate the measurement of: Intact parathyroid hormone (iPTH) and serum total calcium (sCa) levels for predicting hypocalcemia after total thyroidectomy (TT)." (PMID 34429957, 2021). "Hypocalcemia stimulates and hypercalcemia suppresses PTH secretion, while the opposite occurs with CT release." (PMID 34181644, 2021). "A PTH ˂ 10 pg/mL measured at 48 h after surgery had a sensitivity, specificity as well as an accuracy of 100%, for predicting hypocalcemia after TT." (PMID 34429957, 2021). "Many studies demonstrate that PTH is a highly sensitive indicator, with high specificity to predict hypocalcemia after TT." (PMID 34429957, 2021). "Cinacalcet has good oral bioavailability and is thus expected to produce systemic effects, including hypocalcemia due to PTH suppression." (PMID 33400691, 2021). "Another possibility is that patients who present with hypocalcemia have pre-existing parathyroid hormone (PTH) and vitamin D imbalances that are exacerbated by SARS-CoV-2 infection." (PMID 34081611, 2021). "Theoretically, patients with reduced serum Vitamin D levels are more prone to develop hypocalcemia due to a higher dependency on PTH induced bone and renal reabsorption mechanisms." (PMID 31492617, 2021). "The cut-off point of PTH has been 10 min after TT was at 23 pg/mL as it was the best compromise between sensitivity and specificity for predicting hypocalcaemia." (PMID 34429957, 2021). "The mean pre-RAI PTH and serum calcium levels in the normal serum calcium group were higher than those in the hypocalcemia group (4.30 ± 1.23 pmol/L vs. 3.74 ± 1.19 pmol/L, P = 0.03 and 2.28 ± 0.09 mmol/L vs. 2.19 ± 0.06 mmol/L, P < 0.001, respectively)." (PMID 34122347, 2021). "Measurement of PTH at any time from 10 min to several hours after thyroidectomy will accurately predict postoperative hypocalcemia." (PMID 34429957, 2021). "Increased parathyroid hormone (PTH) secretion is an appropriate homeostatic response to correct the resultant hypocalcemia." (PMID 34580590, 2021). "A total of 37 patients (63%) in the group of PTH < 12 pg/mL developed a temporary postoperative hypocalcemia, compared to 33 patients (25.4%, p < 0.01) in the group of PTH > 12 pg/mL." (PMID 34575224, 2021). "The original trial noted divergent rates of postoperative hypocalcaemia when stratified by day 1 postoperative PTH status." (PMID 33498810, 2021). "Hypocalcemia is less likely in the presence of a normal PTH level, so PTH can facilitate the patient's discharge within 24 h." (PMID 34429957, 2021). "A ROC curve analysis was performed to evaluate the influence of postoperative PTH level and postoperative PTH reduction ratio on postoperative hypocalcemia." (PMID 34956363, 2021). "Within the current study, 10 min PTH measurement post-thyroidectomy can be used as an indicator of hypocalcemia with (95%) accuracy, which avoids postoperative calcium supplementation and favors early postoperative hospital discharge." (PMID 34429957, 2021). "Mg-depleted patients with hypocalcemia despite high PTH levels suggest bone and kidney resistance to PTH." (PMID 33435521, 2021). "A decrease in serum ionized Ca+2 (hypocalcemia) inactivates the CaSR in the parathyroid glands and subsequently stimulates PTH secretion." (PMID 33542868, 2021). "The best time to evaluate PTH after thyroidectomy in order to accurately predict post-operative hypocalcemia remains under debate." (PMID 34574074, 2021).
Hypocalcemia (continued). "Relative hypoPT requires treatment due to symptoms and/or signs of hypocalcemia despite the normal range of serum PTH and calcium levels, which is of some clinical significance." (PMID 34474672, 2021). "In our study, postoperative hypocalcemia developed in 36.5% of patients, while a total of 59 patients (31.1 %) had a postoperative PTH level < 12 pg/mL." (PMID 34575224, 2021). "Overall, patients with postoperative hypocalcemia had 70.6% lower PTH levels compared with preoperative levels, and this difference was even more pronounced in patients with postoperative PTH levels < 12 pg/mL (92%)." (PMID 34575224, 2021). "They showed hypocalcemia, hyperphosphatemia, normal PTH and urinary calcium, while magnesium was at the lowest level." (PMID 34160437, 2021). "Most studies have shown that calcium intake decreases PTH levels, which is logical since PTH is released in hypocalcemia." (PMID 35008468, 2021). "Activated osteoblasts result in increased receptor activator of nuclear factor kappa-Β ligand (RANKL) concentration, hypocalcemia, and parathyroid hormone release that respond to hypocalcemia." (PMID 34611139, 2021). "Detection of the incidence of hypocalcaemia, variation in perioperative calcium level, variation in perioperative PTH level and cut off level of PTH as a predictor of hypocalcaemia after TT." (PMID 34429957, 2021). "When a low intact parathyroid hormone (PTH) level is accompanied by hypocalcemia, hypoparathyroidism will occur." (PMID 34262932, 2021). "Indirect effects on PTH secretion occur through diminished intestinal absorption of calcium resulting in hypocalcemia." (PMID 33784965, 2021). "Low serum PTH concentrations in the immediate postoperative period are a good marker for the development of postoperative hypocalcemia; however, its ability to predict long-term or permanent hypoparathyroidism is very limited." (PMID 33953701, 2021). "All patients who developed a definitive hypocalcemia had a 1-day postoperative PTH level < 1 pg/mL, and a postoperative PTH level < 5 pg/mL was a strong predictive factor for definitive hypoparathyroidism (OR = 24.5 (95% CI 2.83–212.51, p < 0.0001)." (PMID 34575224, 2021). "In animal models, induced hypocalcemia increased PTH levels 10- to 12-fold to restore serum calcium homeostasis." (PMID 34200767, 2021). "In the late stages of CKD, hyperphosphatemia, decreased production of 1,25(OH)2D, and hypocalcemia promote PTH-mRNA transcription and PTH formation, leading to SHP." (PMID 34408941, 2021). "Auxiliary examinations demonstrated hypocalcemia, hyperphosphatemia, normal parathyroid hormone level and nephrolithiasis." (PMID 34160437, 2021). "The increase in serum PTH concentrations occurred in parallel with the decrease in Ca2+ concentrations, supporting the rapid response of this system to protect against hypocalcemia." (PMID 34181644, 2021). "The appropriate homeostatic response to hypocalcemia is increased parathyroid hormone (PTH) secretion from the parathyroid glands." (PMID 34580590, 2021). "PTH and hypocalcemia enhance CYP27B1 pathway-mediated hydroxylation of 25D to its active form: 1,25D." (PMID 33804453, 2021). "Some definitions only required reduction in serum calcium levels, while others required reduction in both calcium and PTH levels in defining hypocalcaemia." (PMID 32700234, 2021). "In the majority of patients with PHP, the most important clinical signs are symptoms of hypocalcaemia due to PTH resistance." (PMID 33920525, 2021). "Univariate analysis revealed that predictors of hypocalcemia in the postoperative period were age, PTH concentration postoperatively, and anatomopathological diagnosis of malignancy." (PMID 31492617, 2021). "•High preoperative parathyroid hormone and calcium need monitoring in post-operative period to avoid hypocalcemia." (PMID 34450530, 2021).
Hypocalcemia (continued). "The development of hypocalcemia depends on several factors, including the catabolism of PTH (some PTH particles continue to have biological activity), vitamin D levels, and the presence of bone mineral disorders." (PMID 34574074, 2021). "Transmission is autosomal recessive, and clinically the phenotype is severe hypocalcemia with high PTH levels (PTH resistance)." (PMID 35299844, 2021). "Our data suggest that the detection of PTH 3 h after thyroidectomy is a reliable marker to predict post-surgical hypocalcemia and to prevent overtreatment of normocalcemia that occurs with routine calcium and/or vitamin D supplementation." (PMID 34574074, 2021). "Postoperatively, PTH and calcium levels need to be monitored as calcium supplementation is sometimes necessary in order to avoid clinical hypocalcemia." (PMID 34450530, 2021). "This process focussed on improving parathyroid hormone (PTH) and calcium blood testing, prophylactic calcium prescribing and the subsequent monitoring and management of hypocalcaemia." (PMID 34164240, 2021). "We demonstrated that a single measurement of serum PTH performed 3 h after thyroidectomy was able to predict the development of hypocalcemia 48 h in advance with an accuracy of 100%." (PMID 34574074, 2021). "Previous studies revealed that hypocalcemia is seen in hypothyroidism this is mainly due to the low levels of PTH and low levels of calcitriol." (PMID 34513512, 2021). "In our case, hypocalcaemia likely resulted from the severe hypomagnesemia mediated by decreased parathyroid hormone (PTH) secretion or PTH resistance." (PMID 33544331, 2021). "The reported incidence of POSH varies widely because different definitions are used (e.g. calcium levels under the lower limit of the normal range, or symptomatic hypocalcaemia, or low PTH levels within 4 h or within 24 h after the operation)." (PMID 33599211, 2021). "The reliability of postoperative 20-min, 1-hour, 2-hour, and 3-hour PTH levels for predicting postoperative hypocalcemia has been confirmed." (PMID 32802056, 2020). "Based on these diverse results, we aimed to accurately investigate the role of low 25(OH)D level in developing hypocalcemia by eliminating PTH level as a confounder." (PMID 32774362, 2020). "Low levels of vitamin D associated with hypocalcemia are known to reduce FGF-23 levels and can directly and indirectly stimulate PTH production." (PMID 33469545, 2020). "Hypoparathyroidism is a rare metabolic disorder characterized by low or inappropriately normal levels of parathyroid hormone leading to hypocalcemia." (PMID 32493404, 2020). "Hypocalcaemia stimulates increased PTH production by the parathyroid glands and elevated phosphate levels stimulate fibroblast growth factor 23 (FGF23) secretion by osteocytes." (PMID 31240395, 2020). "The initial laboratory investigation showed elevated parathyroid hormone level (311.2 pg/mL), hypocalcemia (albumin-corrected serum calcium 4.3 mg/dL), hypocalciuria, hyperphosphatemia, hypophosphaturia, and vitamin D deficiency." (PMID 33320452, 2020). "Hypoparathyroidism (HP) and pseudohypoparathyroidism (PHP) are rare diseases due to parathyroid hormone (PTH) insufficiency or resistance leading to hypocalcemia, hyperphosphatemia and related symptoms." (PMID 32393234, 2020). "Surgeons discovered that the postoperative 1-hour PTH level had equivalent reliability to the postoperative day 1 PTH for predicting the development of symptomatic hypocalcemia." (PMID 32802056, 2020). "Surgeons reported that the postoperative 1-hour PTH level is reliable for predicting the development of postoperative symptomatic hypocalcemia." (PMID 32802056, 2020). "Both preoperative 25(OH)D level and postoperative PTH level have been reported as independent predictors for postthyroidectomy hypocalcemia." (PMID 32774362, 2020).